LINC01714 (long independently transcribed non-coding RNA 1714)
Gene: Long non-coding RNA gene on chromosome 1 (8,158,695 to 8,215,242, forward strand). Ensembl gene ENSG00000227634.
Diseases named in the same sentence as LINC01714 in open-access papers:
LINC01714 is named in the same sentence as 2 diseases in open-access papers, as found by Europe PMC text mining. Sharing a sentence is not in itself a finding about the gene and the disease. The quoted sentences say what the papers report.
gastric cancer (1 paper, 2021). A primary or metastatic malignant neoplasm involving the stomach. "A total of 63 prognostic-associated eRNAs in gastric cancer were identified, the top 6 eRNAs were LINC01714, ZNF192P1, AC079760.2, LINC01645, EMX2OS, and AC114489.2." (PMID 34731149, 2021). "The results demonstrated that higher expression levels of LINC01714, ZNF192P1, AC079760.2, LINC01645, EMX2OS, and AC114489.2 were significantly associated with the poor survival of gastric cancer patients." (PMID 34731149, 2021).
LINC01714 also shares sentences with these, for which no sentence is quoted: cholangiocarcinoma (1 paper).